HMGB1 (high mobility group box 1)
Diseases named in the same sentence as HMGB1 in open-access papers (continued):
Sharing a sentence is not in itself a finding about the gene and the disease.
viral infection (75 papers, 2008 to 2025). "It should be noted that the key reason why HMGB1 acts as a cytokine and then causes inflammatory responses during virus infection is that HMGB1 is released from the nucleus to the extracellular milieu." (PMID 37559147, 2023). "Another chromatin-associated protein-derived DAMP, HMGB1, which can be secreted from dying cells during viral infection, is also sensed by the TLR4 co-receptor MD-2." (PMID 36678520, 2022). "In other viral disease models, HMGB1 complexes with viral and damage-associated molecules, which are endocytosed by macrophages, and activates inflammasome and cell death pathways." (PMID 34444232, 2021). "In fact, elevated serum HMGB1 levels are associated with a variety of diseases and can be used as biomarkers to predict disease progression, including viral diseases." (PMID 33313438, 2020). "Anti-HMGB1 also significantly reduced the viral infection in the lungs of RAGE deficient mice, and significantly increased IFNα4 and IFNγ expression in the lung compared to mice treated with the isotype control." (PMID 28099113, 2017). "HMGB1 was linked to play a potential role in sepsis, hemorrhagic shock, trauma and several infectious viral diseases." (PMID 27348219, 2016). "However, excessive extracellular HMGB1 during virus infection has been associated with the pathogenesis of diseases." (PMID 35058496, 2022). "However, the UPR may also be triggered by disruptions in homeostasis, viral infections, or damage-associated inflammatory factors, such as the high mobility group box-1 protein (HMGB1) in DCs." (PMID 35069537, 2021). "At this time, we do not know how Eritoran blocks release of HMGB1 into serum after virus infection; however, we hypothesize that epithelial necroptosis caused by influenza virus infection leads to release of HMGB1 that, in turn, engages TLR4 and can be blocked by both Eritoran and P5779." (PMID 29535197, 2018). "For the first time, we integrated these findings and demonstrated that during recombinant virus infection, HMGB1 binds to TLR4 on macrophages, activating the MyD88-NFκB-NLRP3 (ASC) pathway and inducing M1 polarization." (PMID 40082916, 2025). "Our findings indicate that FBP primarily promotes the lysosomal degradation of HMGB1, leading to reduced levels of HMGB1 protein during viral infection." (PMID 39693295, 2024). "Studies have revealed that HMGB1 plays multifaceted roles in viral replication cycles, thereby either promoting or restricting viral infection in a manner dependent on the viral strain and cellular context." (PMID 38707036, 2024). "Together, these findings indicate that FBP primarily reduces HMGB1 protein levels by promoting its lysosomal degradation during viral infection." (PMID 39693295, 2024). "In recent years, the inflammatory effect of HMGB1 has received increasing attention in viral diseases." (PMID 37559147, 2023). "In recent years, necrotic cells’ HMGB1 protein has been shown to contribute to a number of viral infections." (PMID 36788994, 2023). "We postulate that trapping of HMGB1 by chrysin contributes in viral infections by decreasing the level of proinflammatory cytokines induced by HMGB1." (PMID 36895013, 2023). "As the viral infection induces the release of HMGB1 and other proinflammatory cytokines, this in turn leads to an increase in the levels of HMGB1 and other proinflammatory cytokines released." (PMID 36788994, 2023). "Caspase-1 cysteine protease activation by inflammasomes is a crucial immune response to viral infections, as it stimulates production of IL-1β, IL-18 and high mobility group box 1 (HMGB1) protein to initiate pronounced inflammatory responses." (PMID 36263798, 2022).
viral infection (continued). "HMGB1 is a vital inflammatory alarmin participating in the etiopathogenesis of a variety of viral infections and inflammatory diseases." (PMID 36059973, 2022). "HCV infection in Huh7 cells is reduced by treatment with HMGB1 inhibitor GA, and the nucleus-cytoplasmic translocation of HMGB1 induced by viral infection is blocked." (PMID 36139393, 2022). "Further studies are needed to clarify the role of HMGB1 along the course of viral infections from mild viral diseases to ARDS." (PMID 36251689, 2022). "As a result, virus infection significantly promoted HMGB1 release in MDBK cells, compared to that of uninfected controls." (PMID 34008469, 2021). "Since β-catenin signaling is essential for cell survival, and our data indicated that iCRT14 promotes cell apoptosis induced by the virus infection, which corroborate the increased release of HMGB1 protein." (PMID 34008469, 2021). "We suggested that virus infection promotes translocation of HMGB1 protein into nucleus, mitochondira, and extracellular spaces, which consequently leads to depletion of cytoplasmic HMGB1." (PMID 34008469, 2021). "Taken these data together, virus infection promotes accumulation of HMGB1 protein in both nucleus and mitochondria." (PMID 34008469, 2021). "Virus infection increases accumulation of HMGB1 protein in both nucleus and mitochondria, and relocalizes nuclear HMGB1 to assemble in highlighted foci via a confocal microscope assay." (PMID 34008469, 2021). "Especially, it is well known that the virus accomplishes most of the replication cycles in the nucleus, and the virus infection promoted accumulation of HMGB1 protein in the nucleus, making it accessible to the de novo virus genome." (PMID 34008469, 2021). "Here, we found that accumulation of HMGB1 in the mitochondria is increased following virus infection, which is a possible protective response to overcome the injury on mitochondria DNA." (PMID 34008469, 2021). "Previous studies have reported that viral infection induces the translocation and secretion of HMGB1." (PMID 34532298, 2021). "In the process of viral infection, HMGB1 is actively or passively released by the infected cells and initiates an inflammatory response driven by the infected cells and the adjacent innate immune cells." (PMID 33664952, 2021). "After virus infection, staining of HMGB1 is predominantly observed in the nucleus, and highlighted staining around the rim of nucleus as observed in uninfected cells was not readily detected." (PMID 34008469, 2021). "In this study, we demonstrate that HMGB1 facilitates BoHV-1 productive infection in MDBK cells, and virus infection at later stage significantly increases HMGB1 release and alters HMGB1 subcellular localization." (PMID 34008469, 2021). "In this study, the effects of HMGB1 had on BoHV-1 productive infection were analyzed via treatment of cells with glycyrrhizin during virus infection." (PMID 34008469, 2021). "When the purified mitochondrial fractions were subjected to detection of HMGB1 protein via Western blot, we found that HMGB1 protein in mitochondria was increased by virus infection, relative to that in mock-infected controls." (PMID 34008469, 2021). "As such the released HMGB1 protein in the extracellular environment and the increased accumulation of HMGB1 in both nucleus and mitochondria attributed to virus infection mainly came from cytosol." (PMID 34008469, 2021). "And the virus infection leads to alteration of HMGB1 signaling by increasing HMGB1 release, increasing accumulation of HMGB1 protein in both nucleus and mitochondria, as well as relocalization of nuclear HMGB1." (PMID 34008469, 2021). "So even though total levels of HMGB1 protein were reduced in cytoplasm, the accumulation in mitochondria is increased following virus infection." (PMID 34008469, 2021). "Consistently, loss of PTENα increased the amounts of HSP70, HSP90, HMGB1, and eATP (extracellular ATP) in TIF in the lung during viral infection." (PMID 34446716, 2021).
viral infection (continued). "Similar to NLRP/HMGB1, which propagates following an autophagy impairment during viral infections, prionoids and AGEs behave as DAMPs to trigger inflammatory reactions within host cells, via RAGEs and TLRs." (PMID 33182802, 2020). "As a direct HMGB1 inhibitor, glycyrrhizin is the main active ingredient of licorice root and has been used in traditional medicine to treat inflammatory and viral diseases, including SARS-CoV." (PMID 33313438, 2020). "In Ad WT-infected cells, the amount of HMGB1 released to the media was significantly reduced as compared to activated mock infected cells suggesting a suppressive effect of the virus infection." (PMID 31849970, 2019). "One of the most abundantly secreted DAMPs following oncolytic virus infection is high mobility group box 1 (HMGB1)." (PMID 29543735, 2018). "Both influenza A and B virus infections induced robust levels of serum HMGB1 levels in a time-dependent manner, although induction profiles differed somewhat among the strains." (PMID 29535197, 2018). "Viral infection often induces HMGB1 secretion, as we show with NIH-3T3 and 3T6 Swiss albino cells infected with HSV1716." (PMID 29543735, 2018). "We also show that HMGB1 secretion following virus infection can be toxic to cell lines in vitro, thereby limiting virus infection and spread." (PMID 29543735, 2018). "HMGB1 is an independent biomarker for the mortality in severe pneumonia, viral infection‐elicited pneumonia or acute respiratory distress syndrome (ARDS)." (PMID 28039939, 2017). "HMGB1 inhibitor or neutralizing antibody also abates immune response to virus infection and tumor antigen via blocking HMGB1/TLR4 signaling pathway." (PMID 28969092, 2017). "Anti-HMGB1 mitigated both early-life viral disease and asthma-like features, highlighting HMGB1 as a possible novel therapeutic target." (PMID 28099113, 2017). "One example is HMGB1 (high mobility group box 1), a DNA binding protein critical for the regulation of type I interferon and inflammatory responses in viral infection." (PMID 29207503, 2017). "Studies on DENV and HCV both suggested that extracellular HMGB1 reduces virus infection and triggers interferon response." (PMID 27634894, 2016). "Elevated levels of HMGB1 were anticipated in patients with hemorrhagic fevers, since it was shown that HMGB1 has a role in many diseases, including infectious viral diseases." (PMID 27348219, 2016). "Given the limited benefit of anti-viral drugs, anti-HMGB1 mAb, which provides a protective effect against the host immunological response, shines new light on the treatment of emerging viral infections." (PMID 26067826, 2015). "These properties of HMGB1 have to be taken into consideration in the context of an uncontrolled viral infection, such as that induced by HIV." (PMID 18974890, 2008). "HMGB-1 levels may be influenced by the gut microbiome, which is known to regulation inflammation and immune response to viral infections." (PMID 38932366, 2024). "However, upon viral infection, HMGB1 is rapidly mobilized and translocated to the cytoplasm and extracellular environment." (PMID 39693295, 2024). "Furthermore, viral infections can alter the pH and functionality of lysosomes, potentially impacting the stability and degradation of HMGB1." (PMID 39693295, 2024). "Our study demonstrated that the binding of FBP to HMGB1 is enhanced during viral infection, which may facilitate lysosome-mediated degradation of HMGB1." (PMID 39693295, 2024). "Finally, among these differentially regulated proteins, we primarily focused on HMGB1 based on its potential effects on viral replication and virus infection-induced inflammatory responses." (PMID 37559147, 2023). "This situation increases the significance of HMGB1 in viral infections." (PMID 36788994, 2023).
viral infection (continued). "Seven days after viral infection with the recombinant virus, the reduced Hmgb1 expression resulted in up-regulation of LXRα-responsive genes, similarly to what is seen in liver of mice with a constitutive Hmgb1 deletion in hepatocytes." (PMID 35333579, 2022). "In addition, it recognizes certain damage-associated molecular patterns (DAMPs) such as high mobility group box 1 (HMGB1) and heat shock proteins (HSPs) released from dying or lytic cells during host tissue injury or viral infection." (PMID 33505220, 2021). "Following virus infection, part of HMGB1 are released into extracellular spaces, while the accumulation in both mitochondria and nucleus is increased, which may culminate in reduced steady-state protein levels of HMGB1." (PMID 34008469, 2021). "We speculated that cytosol is the major source of HMGB1 protein flowing into different directions driven by virus infection." (PMID 34008469, 2021). "Thus we suggested that cytosol HMGB1 protein is the source accounting for HMGB1 flowing to different directions induced by virus infection." (PMID 34008469, 2021). "Taken together, it is highly possible that the accumulated HMGB1 in both nucleus and mitochondria may facilitate DNA damage repair induced by virus infection, which is an interesting question to be addressed in the future." (PMID 34008469, 2021). "And iCRT14 promotes further translocation of HMGB1 into mitochondria following virus infection." (PMID 34008469, 2021). "The depletion of RAGE protein following virus infection may have influence on the signaling transduction stimulated by released HMGB1." (PMID 34008469, 2021). "In addition, we found that relative to the mock-infected controls, HMGB1 protein levels were increased in the nucleus fractions, but decreased in the cytoplasmic fractions following virus infection." (PMID 34008469, 2021). "Instead, HMGB1 mainly locates at the nucleus following virus infection." (PMID 34008469, 2021). "HMGB1 is involved in the pathogenesis of a variety of viral diseases." (PMID 32070432, 2020). "We postulated that HMGB1 secretion in response to virus infection could serve as a cytotoxic means of restricting virus infection." (PMID 29543735, 2018). "In the context of an active virus infection, HMGB1 bound to viral nucleic acids could act as an adjuvant that ultimately exacerbates inflammatory responses thereby promoting cell death, immunity, and sensitization to antineoplastic drugs." (PMID 29543735, 2018). "The data presented herein raise the intriguing possibility that blocking HMGB1 may be a novel and effective treatment for early life viral infections and a possible preventative for asthma onset." (PMID 28099113, 2017). "On the contrary, NIC treatment promoted HMGB1 acetylation/release and virus infection." (PMID 27634894, 2016). "HMGB1 has been proposed to be a crucial mediator in the pathogenesis of many diseases, including sepsis, autoimmunity, acute lung inflammation and several severe viral infections." (PMID 26067826, 2015). "The recent increase in HMGB1 studies may be attributed to its role in many diseases, ranging from viral infections to autoimmune disorders and cancer." (PMID 24255708, 2013). "Whereas the role of HMGB1 during bacterial infections has been extensively investigated, notably during severe sepsis, its dynamics and potential impact during viral infections remain largely unknown." (PMID 21283827, 2011). "Interestingly, we found that, in contrast to the reported findings, ERK1/2 phosphorylation was significantly downregulated in HNSCC cells infected with either wtVSV or VSV-S, suggesting that increased HMGB1 during viral infection cannot promote tumor growth via ERK1/2 activation." (PMID 39789615, 2025).
viral infection (continued). "Furthermore, TLR4 has been found to recognize certain damage-associated molecular patterns (DAMPs), e.g., high mobility group box 1 (HMGB1) and heat shock proteins (HSPs), which are released from dying or lytic cells during host tissue injury or viral infection." (PMID 38791489, 2024). "However, recent research showed that cells undergoing programmed death following bacterial or viral infection release signals, including surface-exposed calreticulin (CRT), damage-associated molecular patterns (DAMPs), and high-mobility-group protein 1 (HMGB1)." (PMID 38067345, 2023). "Hence, HMGB1 is expected to be a promising therapeutic target for viral diseases." (PMID 37559147, 2023). "Therefore, preventing the overproduction of extracellular HMGB1 could be a therapeutic approach against the pathogenesis of viral infection." (PMID 35058496, 2022). "Therefore, HMGB1 is accepted as a prognostic biomarker of disease severity due to viral infection." (PMID 34008469, 2021). "Since the cytoplasm fractions purified by using nucleus isolation kit (Beyotime Biotechnology, cat# P0027) contain mitochondria, and virus infection promotes accumulation of HMGB1 in mitochondria, we wondered whether the translocation to mitochondria is affected by iCRT14." (PMID 34008469, 2021). "While whether HMGB1 is involved in virus infection-induced DDR is currently unknown." (PMID 34008469, 2021). "Thus as a control it validates the findings that virus infection promotes HMGB1 release." (PMID 34008469, 2021). "However, detailed mechanism of HmgB1 role in viral infection remains to be determined." (PMID 33114717, 2020). "Therefore, better cell culture model for PEDV is necessary to clarify whether released HMGB1 inhibits virus infection when IFN-α or IFN-β gene is present." (PMID 27634894, 2016). "Both TLR2 and TLR4 have been associated with recognition of DAMPs released from necrotic infections, including heat shock proteins (HSPs), high mobility group box-1 (HMGB1) protein, and oxidized phospholipids, all of which may be released during virus infections." (PMID 23435233, 2013). "During viral infections, FBP predominantly reduces the protein levels of HMGB1 by facilitating its lysosomal degradation." (PMID 39693295, 2024). "This possibility is further corroborated by its chemokine-like role and pro-inflammatory properties that may be inhibited by cationic ribosomal proteins RPL9 in LPS + HMGB1-stimulated TNF-α expression in macrophage-like RAW264.7 cells or in viral infections." (PMID 39494346, 2024). "The viral-infection-mediated release of HMGB1 triggers pro-inflammatory responses similar to those of LPS and thus supports the significance of the therapeutic potential of TLR4/MD-2 antagonists for symptom release in viral disease." (PMID 36678520, 2022). "For example, G2/I2 showed hyper-editing of type 1 interferon (IFN) receptors (IFNAR1 and IFNAR2), type 1 IFN-stimulated genes (ISGs) (e.g., EIF2AK2, DDX58/RIG-1, MAVS, TRIM56, and TRIM69) and genes involved in immune responses to viral infection (EIF2AK2, DDX58/RIG-1, MAVS, CASP8, CYCS, and HMGB1)." (PMID 35406793, 2022). "In addition to HMGB1 and ATF3, other target genes at the HBV/HCV shared GWS loci are involved in both autophagy and immune signaling pathway to virus infection." (PMID 34458256, 2021). "Relative to the uninfected cells, the mRNA expression levels of HMGB1 are increased to approximately 1.55-fold following virus infection, but not affected by the UV-inactivated virus." (PMID 34008469, 2021). "Obviously, the decreased steady-state protein levels of HMGB1 did not corroborate the increased mRNA levels in response to virus infection." (PMID 34008469, 2021). "After TACE, the upregulated HMGB1 often occurs in normal-weight people without virus infection, which is also a group of people with better PFS/OS outcomes than others." (PMID 34583662, 2021).